SOST (sclerostin)
Diseases named in the same sentence as SOST in open-access papers (continued):
Sharing a sentence is not in itself a finding about the gene and the disease.
chronic kidney disease (76 papers, 2013 to 2026). Impairment of the renal function secondary to chronic kidney damage persisting for three or more months. "On the other hand, in end-stage renal disease patients receiving treatment with HD or hemodiafiltration low sclerostin levels were associated with higher symptoms of coronary heart disease and rhythm disturbance." (PMID 39078512, 2024). "This latter association prompted us to exclude cases of SLE with chronic kidney disease in order to avoid its possible role as a confounding factor in the association between sclerostin and cardiovascular risk." (PMID 36517533, 2022). "sclerostin accumulates in the serum of patients with chronic kidney disease (CKD) and was associated with bone disease." (PMID 35600583, 2022). "Sclerostin, bone formation antagonist is in the spotlight as a potential biomarker for diseases presenting with associated bone disorders such as chronic kidney disease (CDK-MBD)." (PMID 26749312, 2016). "A high level of sclerostin in chronic kidney disease patients is associated with the pathogenesis of bone disorders such as an increased fracture risk and correlates positively with serum 1,25(OH)2D3, phosphorus, and TNF-α, indicating a decrease in the bone turnover rate." (PMID 32708317, 2020). "Growing evidence suggests that circulating Wnt signalling inhibitors such as DKK-1 and sclerostin may crucially contribute to the pathogenesis of chronic kidney disease-associated bone mineral disorder (CKD-MBD)." (PMID 27313945, 2016). "Sclerostin may also play a role of importance in patients with chronic kidney disease associated with mineral and bone disorder." (PMID 26749312, 2016). "Although the role of Sclerostin in chronic kidney disease is not fully understood, previous research has indicated that inhibiting Sclerostin may be a potential strategy for treating skeletal and vascular complications associated with chronic kidney disease." (PMID 38714960, 2024). "Nevertheless, other studies have shown that higher serum sclerostin levels increase all-cause mortality in patients with chronic kidney disease (CKD)." (PMID 31677125, 2020). "In patients with end-stage renal disease, circulating levels of SOST can reach 2–4 times those of the normal population." (PMID 40563496, 2025). "Elevated sclerostin levels have been reported in chronic kidney disease, with a significant increase with disease progression, as well as in type 2 diabetes and in the elderly." (PMID 39747949, 2025). "In other clinical studies serum sclerostin levels were related to vascular calcification in 51 patients with end-stage renal disease." (PMID 36895513, 2023). "We found a significant increase in sclerostin and DKK-1 in the PMWCNT-instilled group, supporting the theory that PMWCNTs can initiate chronic kidney disease-associated bone and mineral disorder through the inhibition of Wnt signaling." (PMID 37112600, 2023). "Boltenstål and colleagues studied a cohort of patients with chronic kidney disease stages 3–5D and showed that sclerostin levels were higher in low bone turnover patients in comparison with non-low bone turnover patients." (PMID 35563144, 2022). "Determination of the sclerostin level is useful in the diagnosis of different pathologies, such as Van Buchem Dam disease, or to study the progression of chronic kidney disease (CKD)." (PMID 36498053, 2022). "In humans, sclerostin was reported to be positively correlated with age and to be higher in men than women even in patients with chronic kidney disease." (PMID 35563144, 2022). "Patients with chronic kidney disease have higher levels of sclerostin in comparison with healthy individuals and serum sclerostin tends to increase as the kidney function declines." (PMID 35563144, 2022). "In two cross-sectional studies of patients with chronic kidney disease, serum sclerostin levels were higher in patients with the lower glomerular filtration rates characteristic of advanced disease." (PMID 33776907, 2021).
chronic kidney disease (continued). "Increased serum sclerostin concentrations (approximately 3-fold increase compared to kidney-healthy controls) have been found in de novo (due to sepsis) or in acute-on-chronic kidney disease." (PMID 34822428, 2021). "In clinical studies, the serum Wnt inhibitor sclerostin was significantly increased in chronic kidney disease patients with intensive vascular calcification." (PMID 33923139, 2021). "In a mouse model of chronic kidney disease-mineral and bone disorder, aortic calcification and circulating sclerostin were significantly increased compared to healthy mice." (PMID 33776907, 2021). "Circulating sclerostin increases by up to four-fold in chronic kidney disease and hemodialysis patients." (PMID 33923139, 2021). "Studies have shown that the expression of serum sclerostin in patients with chronic renal disease was higher than that in healthy population." (PMID 34976409, 2021). "Because of the frequency of bone phenotypes in patients with chronic kidney disease, the role of circulating sclerostin has been studied extensively in this population." (PMID 33776907, 2021). "In support of a protective role for sclerostin, a multivariate logistic regression model of patients with chronic kidney disease found that lower circulating sclerostin was significantly associated with aortic calcification." (PMID 33776907, 2021). "Compared to healthy individuals, end-stage renal disease (ESRD) patients have serum sclerostin levels that are three to four times higher." (PMID 32366042, 2020). "Serum sclerostin levels are known to be increased in the elderly and in patients with chronic kidney disease." (PMID 32366042, 2020). "Sclerostin is a hormone contributing to the bone-vascular wall cross talk and has been implicated in cardiovascular events and mortality in patients with chronic kidney disease (CKD)." (PMID 32816133, 2020). "FGF23 is considered as a marker of numerous conditions such as chronic kidney disease, in which osteocyte sclerostin and FGF23 are elevated." (PMID 32708317, 2020). "Serum sclerostin levels have also been reported to correlate with the calcification of the abdominal aorta in patients with chronic kidney disease." (PMID 31698687, 2019). "Data concerning the relation between increased levels of circulating sclerostin (a physiological inhibitor of bone formation) and bone turnover in patients with chronic renal failure (CRF) are limited." (PMID 30584645, 2019). "In patients with end-stage renal disease, sclerostin concentrations are several-fold higher than those in subjects with normal renal function." (PMID 31847451, 2019). "Recently published data are contradictory, in terms of the relationship between sclerostin and mortality in subjects with chronic kidney disease." (PMID 29928063, 2018). "Circulating sclerostin levels increase with severity of chronic kidney disease (CKD) and are reported to reach levels that are 2 to 4-fold higher in patients with end stage renal disease as compared to individuals with normal renal function." (PMID 28493902, 2017). "Relationships of Sclerostin, a bone anti-anabolic protein, with biomarkers of mineral bone disorders in chronic kidney disease are still unsettled, in particular in kidney transplant (KTR)." (PMID 28558021, 2017). "Data on the correlation of serum sclerostin and chronic kidney disease (CDK) is scarce and controversially reported." (PMID 27666393, 2016). "Serum sclerostin level was analyzed by ELISA, and renal function was assessed by estimated glomerular filtration rate (eGFR) using chronic kidney disease epidemiology collaboration (CKD-EPI) equation." (PMID 25053944, 2014). "Studies have found that diseases of extra-bone organs, such as atherosclerosis, aneurysm, chronic kidney disease, and cirrhosis, may be related to the expression of SOST." (PMID 40563496, 2025). "Elevated serum sclerostin levels observed in chronic kidney disease may result from several factors, including renal retention of sclerostin." (PMID 40943516, 2025).
chronic kidney disease (continued). "This dual nature is particularly evident in chronic kidney disease patients, where elevated sclerostin levels correlate with increased cardiovascular events, yet simultaneously show potential cardioprotective properties through the regulation of vascular calcification." (PMID 39767786, 2024). "We found that this variant showed a robust negative effect on sclerostin in all cohorts; however, the genetic effect estimate was particularly large in the 4D cohort, comprising individuals with end‐stage chronic kidney disease (CKD)." (PMID 37096546, 2023). "Several studies have reported higher serum sclerostin level in chronic kidney disease (CKD) patients with cardiovascular events, such as coronary and aortic calcification and the effect of sclerostin levels on CVD and all-cause cardiovascular mortality in patients with CKD." (PMID 37919715, 2023). "Sclerostin concentrations are elevated in patients with chronic kidney disease (CKD)." (PMID 36675692, 2022). "Moreover, due to the heterogeneity in enrolled subject cohorts, the impact of serum sclerostin on clinical outcome in chronic kidney disease remains controversial." (PMID 35546224, 2022). "Finally, in end-stage renal disease, coronary artery & epigastric artery calcification positively correlated with serum sclerostin." (PMID 33776907, 2021). "This along with immunohistochemistry of bone biopsies from chronic kidney disease patients suggests that increased production of sclerostin by osteocytes may be a factor in the development of chronic kidney disease." (PMID 33776907, 2021). "Most previous papers focused on sclerostin in patients with moderate/severe chronic kidney disease." (PMID 33800939, 2021). "It has been suggested that the increase in sclerostin protein in chronic renal disease patients might be related to the increase in osteocyte production." (PMID 34976409, 2021). "Furthermore, many of these studies were performed in the context of chronic kidney disease where sclerostin also correlates with age, male gender, and glomerular filtration rate, so its individual effect on the vasculature is difficult to discern." (PMID 33776907, 2021). "Thus, canonical Wnt signaling inhibitors, such as sclerostin and DKK-1, are presumably negative regulators of AS; indeed, in several studies, serum sclerostin was significantly increased in chronic kidney disease patients with intensive vascular calcification." (PMID 33923139, 2021). "The present study investigated the association between sclerostin, renal function, and carotid artery atherosclerosis in non-dialysis patients with stage 3–5 chronic kidney disease (CKD 3–5ND)." (PMID 32458213, 2020). "Mounting evidence indicates that circulating sclerostin may qualify as a biomarker of chronic kidney disease mineral and bone disorder (CKD-MBD)." (PMID 31756992, 2019). "Our results show, for the first time, that serum sclerostin is a factor independently associated with cardiovascular mortality in a study population without end-stage renal disease (ESRD)." (PMID 29928063, 2018). "Whereas several studies have investigated associations of serum sclerostin with disorders of bone, vascular disease, chronic kidney disease (CKD), and mortality, so far, no prospective or controlled studies are available concerning the role of sclerostin in nephrolithiasis." (PMID 38186870, 2024). "The significance of sclerostin for bone and cardiovascular health in patients with chronic kidney disease (CKD) is complex and incompletely understood." (PMID 34822428, 2021). "Furthermore, an excessive accumulation of sclerostin was shown to inhibit PTH secretion in patients with chronic kidney disease, which may potentially slow an excessive bone turnover, induced by secondary hyperparathyroidism." (PMID 30584645, 2019).
chronic kidney disease (continued). "Mounting evidence indicates that sclerostin, a well-known inhibitor of bone formation, may qualify as a clinically relevant biomarker of chronic kidney disease-related mineral and bone disorder (CKD-MBD), including abnormal mineral and bone metabolism and extraskeletal calcification." (PMID 31756992, 2019). "Moreover, serum sclerostin levels were found to be positively associated with brachial-ankle PWV values in kidney transplantation patients, and positively associated with cfPWV values in chronic kidney disease (CKD), hemodialysis, and postmenopausal women." (PMID 30482161, 2018). "For these reasons, recent clinical studies aim to evaluate Sclerostin as a new biomarker of bone disease specifically in chronic kidney disease (CKD)." (PMID 28558021, 2017). "Atherosclerosis, aneurysm, chronic kidney disease (CKD), liver cirrhosis, and other extra-osseous organ diseases may be related to SOST expression." (PMID 40563496, 2025). "However, in chronic kidney disease, the expression levels of Sclerostin are often elevated, particularly during or after CKD stage III." (PMID 38714960, 2024). "This association may be related to pathophysiological alterations in chronic kidney disease, such as secondary hyperparathyroidism, altered metabolism of the active form of vitamin D, phosphorus retention, chronic metabolic acidosis, increased levels of sclerostin and FGF23." (PMID 37507659, 2023). "Thus, the therapeutic target of the chronic kidney disease-mineral bone disorder may be vascular osteoblastic transdifferentiation, and sclerostin levels may be a useful biomarker for the diagnosis of the chronic kidney disease-mineral bone disorder and the progress of its therapy." (PMID 36776982, 2023). "Nevertheless, a positive correlation between sclerostin and BMD has additionally been noted in chronic kidney disease, postmenopausal osteoporosis and rheumatoid arthritis." (PMID 36612090, 2022). "FE of sclerostin, MCP-1, and a couple of other proteins have been reported to be useful in assessing renal injury or monitoring chronic kidney disease." (PMID 36091001, 2022). "Some studies proved that sclerostin concentrations are higher in diabetic patients, with and without chronic kidney disease, in comparison with non-diabetic individuals." (PMID 36675692, 2022). "In non-dialysis chronic kidney disease patients, OPG and sclerostin both proved to be strongly associated with arterial calcification." (PMID 33923139, 2021). "In addition, we did not account for comorbidities such as chronic kidney disease or metabolic syndrome, which are known to alter sclerostin levels." (PMID 41594249, 2026). "Thus, the target of therapy in the chronic kidney disease-mineral bone disorder is not inhibition of sclerostin function, which would intensify vascular calcification." (PMID 36776982, 2023). "Higher cardiovascular risk in patients undergoing MHD is partly explained by chronic kidney disease-mineral bone disorder (CKD-MBD), in which sclerostin plays an important role." (PMID 30314461, 2018). "We analyzed serum sclerostin and DKK1 in 308 patients across the stages of chronic kidney disease (kDOQI stage 1–2 n = 41; CKD stage 3 n = 54; CKD stage 4–5 n = 54; hemodialysis n = 100; peritoneal dialysis n = 59) as well as in 49 healthy controls." (PMID 28493902, 2017). "As previously noted, women with chronic kidney disease were not included in the study, which implies a lower prevalence of CVD in the sample that, in turn, could have led to an underestimation of the association between sclerostin and cardiovascular risk." (PMID 36517533, 2022). "However, elevated sclerostin levels have been found in patients with CVD and chronic kidney disease (CKD), two groups who typically have osteofragilitas." (PMID 34572351, 2021).
chronic kidney disease (continued). "Although the biological relevance of circulating protein measurements has not been fully elucidated, several clinical studies showed altered sclerostin and DKK-1 concentrations in metabolic bone diseases, in type 1 and 2 diabetes mellitus and in patients with chronic kidney disease (CKD)." (PMID 32640551, 2020). "Sclerostin concentrations increase with the development of CKD and are almost threefold higher in patients with end-stage renal disease than in individuals without renal failure." (PMID 36675692, 2022).